MOG (myelin oligodendrocyte glycoprotein)
Diseases named in the same sentence as MOG in open-access papers (continued):
Sharing a sentence is not in itself a finding about the gene and the disease.
transverse myelitis (continued). "This cross-sectional study examines clinical and radiological outcomes among patients with myelin oligodendrocyte glycoprotein (MOG) antibody (Ab) disease or aquaporin-4 (AQP4)-Ab disease after experiencing a first transverse myelitis episode." (PMID 31596489, 2019). "This is the first report of a patient with longitudinally extensive transverse myelitis with an extremely high titer of MOG antibodies after an influenza infection." (PMID 25434485, 2014). "Our case report supports a relationship between anti-MOG antibodies and longitudinally extensive transverse myelitis, which was triggered by influenza infection." (PMID 25434485, 2014). "We diagnosed him with anti-MOG antibody-positive longitudinally extensive transverse myelitis, and started immunosuppression therapy with intravenous methylprednisolone (1000 mg/day) for three consecutive days, followed by oral prednisolone (60 mg per day)." (PMID 25434485, 2014). "Patients with MOG-IgG may have silent brain or optic nerve lesions, detected in 33-50% of patients with clinical transverse myelitis and MOG-IgG." (PMID 40547008, 2025). "Literature review has yielded no other case reports of MOG-associated transverse myelitis in the context of post-COVID-19 infection." (PMID 35399911, 2022). "Although fatigue was worse in AQP4‐Ab patients compared to MOG‐Ab patients (P = 0.008) in all patients as well as in those who ever had transverse myelitis (P = 0.023), this was driven by the differences in age, disability and pain interference rather than antibody subtype itself." (PMID 32187851, 2020). "These autoantibodies, together with anti-myelin oligodendrocyte glycoprotein (MOG) antibodies, should be tested in spinal cord presentations, especially in the context of “longitudinally extensive transverse myelitis” where inflammation extends over at least three vertebral segments." (PMID 29928273, 2018). "Greatest CSF MOG antibody titers were observed for transverse myelitis." (PMID 29064441, 2017). "While MOG-IgG had initially been thought to play a role in classical multiple sclerosis (MS), recent studies have demonstrated that MOG-IgG are in fact a marker of autoimmune optic neuritis (ON) and (often longitudinally extensive) transverse myelitis." (PMID 27802825, 2016). "Thus, the clinical phenotype of relapsing transverse myelitis may warrant consideration of alternative diagnoses, particularly if MOG‐IgG results are inconsistent." (PMID 40059389, 2025). "Ninety-six percent of MOG-IgG-positive children presented with a combination of ADEM, ON, and transverse myelitis (TM)." (PMID 35669399, 2022). "Autoantibodies targeting myelin oligodendrocyte glycoprotein (anti-MOG-IgG) are a marker of several central nervous system inflammatory demyelinating disorders, including ADEM, bilateral optic neuritis, transverse myelitis, and brainstem encephalitis." (PMID 35757742, 2022). "The presence of a short segment (<3 vertebral segments) transverse myelitis (i.e., SSTM) was reported in 14% of patients with AQP4-NMOSD and most recently in patients with MOG-NMOSD." (PMID 29064441, 2017). "A quarter of the MOG-seropositive (1/4) and about a third of the AQP4-seropositive (10/31) and seronegative (4/13) patients had a disease manifestation with transverse myelitis (TM)." (PMID 25889963, 2015). "Over 50% of patients with MOG-IgG and a first demyelinating event have CSF pleocytosis, which is defined by white cell counts of more than 5 cells per μL and is also more common in ADEM or transverse myelitis patients and during attacks." (PMID 40547008, 2025). "Differential diagnoses included NMOSD and MOGAD, which were excluded based on characteristic radiologic patterns, negative aquaporin-4 and MOG antibodies, and the absence of longitudinally extensive transverse myelitis." (PMID 41503332, 2025).
transverse myelitis (continued). "Important discoveries, such as antibodies to aquaporin-4 and myelin oligodendrocyte glycoprotein (MOG) are not accounted for in current clinical criteria of transverse myelitis." (PMID 33101167, 2020). "However, anti-MOG antibodies are not specific and have been detected in patients with ON, transverse myelitis and NMOSD." (PMID 33917395, 2021). "Diagnostic criteria for MOG encephalomyelitis include serum and/or CSF MOG-IgG positivity, any neurological disease (including ADEM, NMO, transverse myelitis, brain or brainstem syndromes), and absence of alternative diagnoses." (PMID 35454978, 2022). "Although the patient tested negative for antibodies to AQP-4 and myelin oligodendrocyte glycoprotein, she was diagnosed with NMOSD in February 2017, based on recurrent episodes of longitudinal extensive transverse myelitis, MRI changes, and area postrema syndrome." (PMID 34025563, 2021).
encephalomyelitis (86 papers, 2015 to 2026). Inflammation of the brain and the spinal cord. "ADEM has been recognized as one of the possible clinical causes of anti-myelin oligodendrocyte glycoprotein (anti-MOG)-associated encephalomyelitis." (PMID 39897230, 2025). "Myelin oligodendrocyte glycoprotein (MOG) immunoglobulin (IgG)-associated encephalomyelitis (MOG-EM; also termed MOG antibody-associated disease, MOGAD) is a relatively newly described entity." (PMID 35737110, 2022). "In around 20% of cases, myelin oligodendrocyte glycoprotein (MOG) immunoglobulin (IgG)-associated encephalomyelitis (MOG-EM; also termed MOG antibody-associated disease, MOGAD) first occurs in a postinfectious or postvaccinal setting." (PMID 35737110, 2022). "We report the diagnosis of myelin oligodendrocyte glycoprotein antibody associated encephalomyelitis (MOG-EM) in a patient who had astrocytoma for several years." (PMID 36221336, 2022). "According to the international recommendations of MOG-IgG-associated encephalomyelitis (MOG-EM) (published in 2018), we decided to make a diagnosis of “possible MOG-EM”." (PMID 33422038, 2021). "Myelin oligodendrocyte glycoprotein antibodies (MOG‐IgG) have been proposed to define “MOG encephalomyelitis” (MOG‐EM), with published diagnostic and “red flag” criteria." (PMID 33047894, 2021). "Currently, myelin oligodendrocyte glycoprotein (MOG)-IgG-associated encephalomyelitis (MOG-EM) is regarded as an independent inflammatory demyelinating disease." (PMID 33419414, 2021). "Nowadays, most experts regard MOG-IgG-associated encephalomyelitis (MOG-EM) as an independent entity, immunopathogenetically distinct from other IDDs." (PMID 33419414, 2021). "Based on clinical, immunological and histopathological evidence, encephalomyelitis associated with MOG antibodies has been regarded as a distinct disease entity different from MS and NMOSD." (PMID 32973780, 2020). "Compared with NMOSD patients, patients with MOG antibody associated encephalomyelitis usually have a single course of the disease and show better recovery of neurological deficits after the attack." (PMID 32973780, 2020). "We have presented the clinical features of a cohort of Chinese patients with MOG-associated encephalomyelitis from Guangdong, China." (PMID 31080435, 2019). "To assess relatedness between anti-MOG-Abs-associated encephalomyelitis in macaques and children, we performed a comparative analysis between species with emphasis on cytokine production at disease onset and IgG and complement deposition in lesions." (PMID 31785610, 2019). "Localization of C deposition has been shown in areas of active demyelination in patients with IgG myelin oligodendrocyte glycoprotein (MOG)-antibody-associated encephalomyelitis and pattern II MS." (PMID 28646890, 2017). "Myelin oligodendrocyte glycoprotein-antibody (MOG-ab)-associated disease (MOGAD) or MOG-immunoglobulin G (MOG-IgG)-associated encephalomyelitis (MOG-EM) has been recognized as a distinct neuroimmunological disorder with specific clinical features and management." (PMID 34691028, 2021). "So, the clinical diagnose was “possible MOG-IgG-associated encephalomyelitis”." (PMID 33422038, 2021). "Alternatively, Miap410 Ab could have had a direct effect by gaining access into the CNS through encephalomyelitis-induced loss in blood-brain barrier that occurs in MOG-induced EAE." (PMID 34591795, 2021). "Of note, the spectrum of MOG antibody-associated encephalomyelitis the last years has expanded to involve cases with TDL and ADEM-like presentation, clinical presentations that could fit to our patient history." (PMID 32714265, 2020). "However, only limited data are yet available on cerebrospinal fluid (CSF) findings in MOG-IgG-associated encephalomyelitis (MOG-EM; also termed MOG antibody-associated disease, MOGAD)." (PMID 32883348, 2020).
encephalomyelitis (continued). "The current discussion evolves toward recognizing this condition as a disease entity distinct from AQP4 ab positive NMOSD and MS for which the acronyms “MOGAD” (MOG antibody associated disease) or “MOG-EM” (MOG antibody associated encephalomyelitis) were proposed." (PMID 32625158, 2020). "Seizures and encephalopathy are common among subjects with MOG-associated encephalomyelitis, and may be associated with cortical and subcortical brain lesions." (PMID 31080435, 2019). "The most common underlying pathology of RAPD is optic neuritis (ON), which can occur in a variety of neuroimmunological disorders such as multiple sclerosis, neuromyelitis optica spectrum disorder, myelin oligodendrocyte glycoprotein antibody associated encephalomyelitis or sarcoidosis." (PMID 30148895, 2018). "Therefore, two research groups independently suggested diagnostic criteria for MOG antibody-associated disorders, the newly introduced entity was termed as “MOG encephalomyelitis”, respectively, “MOG IgG associated disorders”." (PMID 30555462, 2018). "There is an ongoing scientific debate as to whether adult patients with MOG antibodies should be diagnosed with NMOSD or whether MOG-antibody associated encephalomyelitis is a disease entity in its own." (PMID 29209434, 2017). "Currently it is debated whether MOG-IgG-associated encephalomyelitis should be classified as an NMOSD subtype or as a separate disease entity." (PMID 27802824, 2016). "Finally, the tilt and complete drop of full donor chimerism observed in patient #2 after rituximab suggests that the MOG-IgG associated encephalomyelitis had been due to a graft-versus-host mechanism which was lost during treatment—unfortunately together with its graft-versus-malignancy effect." (PMID 33875720, 2021). "We aimed to investigate whether the brain lesion distribution criteria could provide additional clues for differentiating MS from NMOSD and myelin oligodendrocyte glycoprotein immunoglobulin G-associated encephalomyelitis (MOG-EM)―particularly at disease onset―in an independent, large Asian cohort." (PMID 29512413, 2019). "In myelin oligodendrocyte glycoprotein antibody disease, a report of encephalomyelitis in the context of a MOG protein-expressing teratoma suggests the potential to rarely occur as a paraneoplastic phenomenon." (PMID 36781586, 2023). "Patient #1 presented as LGI1- and GAD-IgG positive immune-mediated encephalitis, patient #2 was diagnosed with MOG-IgG positive encephalomyelitis, and patient #3 had chronic inflammatory polyneuropathy associated with SSA(Ro)-IgG positive Sjögren’s syndrome." (PMID 33875720, 2021). "Immunization of mice with MOG readily induces severe encephalomyelitis, suggesting that MOG-specific T cells are present in healthy mice." (PMID 34149706, 2021). "Female C57BL/6 mice intravenously infected with 1 × 106 viable C. tropicalis yeasts were, after three days of infection, immunized with a myelin oligodendrocyte glycoprotein peptide (MOG35–55) to develop encephalomyelitis." (PMID 34575795, 2021). "MOG-IgG is now considered as a separate disease entity from both MS and NMO, referred to as MOG-IgG-associated encephalomyelitis (MOG-EM)." (PMID 34327021, 2021). "Both AQP4-IgG-seropositive NMOSD and MOG-IgG-seropositive encephalomyelitis follow a mostly relapsing-remitting disease course and - as humorally mediated autoimmune diseases - should be distinguished from MS in terms of pathogenesis, prognosis, and therapy." (PMID 33324914, 2020). "Cynomolgus macaques immunized with recombinant human MOG (rhMOG) in incomplete Freund’s adjuvant (IFA) develop an acute encephalomyelitis, with brain magnetic resonance imaging (MRI) and demyelinating lesions reminiscent to that described in ADS." (PMID 31785610, 2019). "Meningoencephalitis has recently been suggested to be a clinical finding typical of myelin oligodendrocyte glycoprotein (MOG) encephalomyelitis." (PMID 31072329, 2019).
encephalomyelitis (continued). "This study demonstrated that the brain lesion distribution criteria can be useful in differentiating MS from NMOSD and MOG-EM, even at disease onset, in a large cohort of Asian patients with idiopathic central nervous system inflammatory diseases." (PMID 29512413, 2019). "MOG-encephalomyelitis often presents with clinical meningoencephalitis symptoms and abnormal CSF findings mimicking central nervous system infection in pediatric and young adult patients." (PMID 31080435, 2019). "As reliable tests for MOG-IgG became available only relatively recently, most of the patients initially received diagnoses other than MOG-IgG-positive encephalomyelitis (EM)." (PMID 27793206, 2016). "Missing OCB or granulocytic pleocytosis should thus prompt physicians to challenge the diagnosis in patients with suspected MS and to consider MOG-IgG- or AQP4-IgG-positive encephalomyelitis." (PMID 27793206, 2016). "In direct comparison, IHC titres were higher on average than those in the majority of patients with AQP4-IgG-positive NMOSD or MOG-IgG-positive encephalomyelitis tested by the authors in recent years using the same methodology." (PMID 27776522, 2016). "Whereas the encephalomyelitis was worse in IL-10-/- mice, the oral administration of myelin glycoprotein of oligodendrocytes (MOG 35–55) result in improvement of disease in all groups." (PMID 26115356, 2015). "At present, a recommendation of diagnostic criteria for MOG encephalomyelitis (MOG-EM) has been proposed; however, there are no unified diagnostic criteria for CCE with anti-MOG antibody." (PMID 37520572, 2023). "However, the severity of induced autoimmune manifestations, such as myelin oligodendrocyte glycoprotein (MOG)-dependent encephalomyelitis (EAE) or graft-vs-host disease (GVHD) is increased relative to wildtype mice." (PMID 35812451, 2022). "As to this point, distinct imaging features of anti-MOG associated encephalomyelitis are not fully established." (PMID 34115143, 2021). "This implies that patients with encephalomyelitis attributed to MOG antibodies may develop bilateral optic nerve and lumbar spinal cord injury." (PMID 32973780, 2020). "We report that cynomolgus macaques immunized with rhMOG/IFA develop an acute encephalomyelitis with a characteristic neuro-inflammatory profile similar to that observed in children with ADS MOG+, but which is different from that seen in children with ADS MOG− including all cases of MS." (PMID 31785610, 2019). "Also, the few existing MRI studies on MOG-IgG seropositive encephalomyelitis suggest a high similarity with MRI features of AQP4-IgG positive patients with the occasional incidence of characteristic fluffy brainstem lesions." (PMID 31258505, 2019). "Currently, there is controversy over whether these MOG-ab seropositive patients are part of the NMOSD disease spectrum or if they belong to a separate disease entity (“MOG-ab positive encephalomyelitis” or MOG-EM)." (PMID 29515685, 2018). "For instance, studies reveal that myelin oligodendrocyte glycoprotein (MOG) formulated with TFA and acetic acid induced encephalomyelitis at comparable incidence and severity levels." (PMID 41301485, 2025). "Seven of 13 MOG-IgG-positive children were initially diagnosed with ON only, 3 children with ADEM + ON, 2 children with NMOSD, and 1 child with encephalomyelitis + ON." (PMID 35869995, 2022). "Eight of 20 MOG-IgG-positive children were diagnosed with recurrent NMOSD, 6 children with recurrent ON (rON), 3 children with ADEM + rON, and 3 children with encephalomyelitis." (PMID 34051804, 2021). "Three of 39 MOG-IgG-positive adults were diagnosed with monophasic NMOSD, 12 with recurrent NMOSD, 14 with encephalomyelitis, 9 adults with rON, and 1 adult with ADEM." (PMID 34051804, 2021).
encephalomyelitis (continued). "To test a possible worsening of encephalomyelitis by non-albicans Candida infection, we used a less severe disease model induced by lower amounts of neuroantigen (MOG) and adjuvant, as we had already employed to test C. albicans’ effect on EAE development." (PMID 35448617, 2022). "Both MOG-IgG-positive encephalomyelitis and AQP4-IgG-positive NMOSD are not usually found in a paraneoplastic context." (PMID 27802825, 2016). "Therefore, MOG-EM should not be excluded easily in astrocytoma patients when the relative antibody of encephalomyelitis is positive." (PMID 36221336, 2022). "Sample No. 2 which showed antibody cross-reactivity between MOG and SARS-CoV-2 N protein was from a 20-year-old unvaccinated female patient who presented with encephalomyelitis after SARS-CoV-2 infection (2021, PCR confirmed infection)." (PMID 38576796, 2024).